MTOR (mechanistic target of rapamycin kinase)
Diseases named in the same sentence as MTOR in open-access papers (continued):
Sharing a sentence is not in itself a finding about the gene and the disease.
tumor (continued). "Reduction in tumor growth was associated with activation of autophagy in HCT116 and HT29 xenografts implicated by LC3B elevation which marks the conjugation of phosphatidylethanolamine to LC3A (an essential step in autophagosome formation) and inhibition of the autophagy negative regulator mTOR." (PMID 29262645, 2017). "However, these antagonistic impacts between oncometabolites and mTOR activity may suggest a possible coordination of lactate and 2-HG for joint tumour promoting functions." (PMID 28578659, 2017). "Thus, combining a dual PI3K/mTOR inhibitor with MEK inhibitors may be a relevant approach to increase anti-tumor activity and prevent drug resistance in patients with LMS." (PMID 28002802, 2017). "Interestingly, in our study not only the dual PI3K/mTOR inhibitor NVP-BEZ235 but also the selective inhibitor RAD001 improved the anti-tumor efficacy of NVP-BGJ398 treatment in both H1703 and LENTI-4 cells, underlining the relevance of mTOR inhibition for SQCLC." (PMID 29190880, 2017). "Therefore, miR-497 and miR-99a may play important suppressive effects on tumor growth controlled by IGF1R/mTOR signaling pathway and would be both biological and clinical targets for future HCC research." (PMID 28624790, 2017). "However, as the ability of pro-apoptosis is growing, the escape pathway of autophagy is triggered, counteracting the anti-tumor effect of mTOR inhibitor and contributing resistence to mTOR inhibitor, which is consistent with the modest anti-tumor effect of mTOR inhibitor in clinical application." (PMID 27177330, 2016). "Therefore, the everolimus benefit observed at countering muscle wasting may result for some degree from a direct mTOR inhibition at the muscle level, while another part may come from its anti-tumor efficacy." (PMID 27462398, 2016). "Furthermore, resistant cells display hyperactivation of the PI3K/mTOR pathway and a highly selective inhibitor against this pathway can efficiently block colony formation, decrease cell proliferation, induce apoptosis and block tumor growth in vivo." (PMID 26999641, 2016). "Tumours that bear wild-type PIK3CA may also respond to PI3K targeted therapy, as we know that the pathway can be activated due to other aberrations such as PTEN loss, AKT or MTOR mutation." (PMID 27765909, 2016). "Interestingly, we found that level of p-AKT protein was significantly up-regulated with a time-dependent manner, suggesting that PD-1/PD-L1 binding could directly activate the intracellular AKT/mTOR oncogenic signaling in DLBCL tumor cells." (PMID 27147575, 2016). "We demonstrated a significant decrease in both tumor growth rate and H295R cell proliferation within the tumor mass in metformin-treated ACC xenografted mice, associated with an increase in AMPK and a decrease in mTOR phosphorylation similar to that observed for in vitro-treated H295R." (PMID 27391065, 2016). "The fact that RER treatment reduced the levels of the phosphorylated AKT and mTOR in tumor cells in our study and that TGF-β was shown to rapidly activate AKT by others suggest that RER might have also neutralized TGF-β signaling in the prostate epithelial cells." (PMID 27863384, 2016). "Thus, we demontrated that DEPTOR negatively regulated the activation of AKT/mTOR pathway which may be responsible for its tumor suppressive function." (PMID 26893358, 2016). "The identification of TNBC tumor types that may respond to mTOR inhibitors remains a major issue." (PMID 27374081, 2016). "mTOR inhibitors may also be considered for shrinkage of a large tumor prior to surgical resection." (PMID 27502586, 2016). "Moreover, Reynisdottir and his colleagues had reported that ZNF703 displayed in tamoxifen resistance induced by activation of the Akt/mTOR signaling pathway and downregulation of estrogen receptor alpha, providing a potential mechanism of its action in tumor growth." (PMID 27764785, 2016).
tumor (continued). "As mRNA of mammalian Target Of Rapamycin (mTOR) is one of the top targets of the miR-99 family, higher levels of these miRs may down regulate mTOR expression, which in turn could inhibit tumor cell growth." (PMID 27738339, 2016). "Therefore, we examined the phosphorylation of AKT, ERK1/2, and mTOR in PPGL tumor samples." (PMID 27990160, 2016). "Based on these premises, we evaluated whether PD-L1 expression was correlated with phosphorylated AKT (p-AKT) expression and overall survival in DLBCL in this study, and then investigated whether PD-1/PD-L1 binding could directly activate intracellular AKT/mTOR pathway in tumor cells." (PMID 27147575, 2016). "However, studies have shown that combined inhibition of multiple steps along the mTOR signaling pathway may lead to sustained responses by targeting mechanisms of tumor resistance." (PMID 27200288, 2016). "In certain tumors mediated by the upregulation of the tyrosine kinase c-Src, it has been suggested that under-expression of miR-99a could be determined by the activation of Src-related pathways with the consequent upregulation of mTOR and the activation of protein synthesis and tumor growth." (PMID 27187382, 2016). "Therefore, the authors concluded that the radio-sensitizing effects of mTOR inhibitors may have derived from the suppression of tumor angiogenesis." (PMID 25887043, 2015). "Currently, it is unknown how these tumor cells are resistant to anti-mTOR treatments." (PMID 25807077, 2015). "Our results provide additional rationale for combination mTOR/MEK inhibitor therapy because in addition to the anti-proliferative effects of MEK inhibitor treatment, mTOR inhibition resulting in enhanced PAK1/JNK/FOXO3-mediated apoptosis could inhibit tumor progression." (PMID 26121028, 2015). "Therefore, Akt hyperactivation may protect tumor cells from energy deprivation by constitutive ATP production and drug-induced apoptosis by mTOR activation, which is highly activated in tumor cells, and contribute to cell survival and growth." (PMID 26158266, 2015). "Thus, it is believed that mTOR increases if the hamartin-tuberin complex is functionally impaired, resulting in dysplasia, tumor formation, and angiogenesis due to accelerated cell proliferation, and thereby causing the systemic manifestation of various symptoms." (PMID 25889454, 2015). "Therefore, besides the general anti-tumor activity obtained by mTOR inhibition, the beneficial bone-sparing result in the BOLERO-2 trial may be explained by at least two effects." (PMID 26468083, 2015). "Since butyrate is also most effective against early stage neoplasms, the crosstalk between mTOR activity and butyrate-mediated Wnt signalling might be important in early colonic tumourigenesis (i.e., adenoma formation, the risk for which typically increases with age)." (PMID 25388238, 2015). "Thus, inhibition upstream to mTOR in the PI3K-Akt pathway might be expected to enhance mTOR inhibition and to exert an anti-tumor effect." (PMID 26059247, 2015). "Furthermore, 11βHSD2 inhibition suppressed lung tumor growth and invasion in association with increased tissue active glucocorticoid levels, decreased COX-2 expression, inhibition of ERK and mTOR signaling pathways, increased tumor endoplasmic reticulum stress as well as increased lifespan." (PMID 26011146, 2015). "Therefore, they could be more suitably treated with agents that target other growth-related requirements of tumors, such as the mTOR pathway that mediates mRNA translation and increase genome instability of tumor cells and initiate their apoptosis." (PMID 26474389, 2015). "It is possible that the combination of mTOR inhibition and radiation may improve the efficacy of tumor radiotherapy via a dual mechanism that promotes radiation-induced tumor cell cytotoxicity and inhibits tumor angiogenesis." (PMID 25009644, 2014).
tumor (continued). "Thus, the different staining frequencies in the different tumor types may also reflect the compartment-dependant diversity of mTOR signaling." (PMID 24593867, 2014). "In addition to conferring mTOR inhibitor resistance, a reduced 4EBP:eIF4E ratio might help to drive the tumor phenotype by facilitating translation of oncogenic mRNAs." (PMID 24586420, 2014). "AKT reactivation induced by mTOR inhibition in tumor cells is likely to reduce its antitumor effects by activating pathways that attenuate its effects on proliferation and apoptosis; thus, it is an unexpected and potentially undesirable consequence of mTOR inhibition." (PMID 25098767, 2014). "In addition, the present case report is the first to analyze the expression of mTOR pathway proteins, which are central proteins involved in carcinogenesis and its inhibitor has been proposed as a therapeutic target for various types of tumor." (PMID 24348822, 2014). "However, none of the tumors disappeared completely, with most maintaining a small volume of residual tumor, suggesting that additional drugs may be necessary in combination with mTOR inhibitors to totally ablate residual disease." (PMID 24708766, 2014). "In addition, mTOR functions in the crosstalk between tumour and endothelial cells." (PMID 25202348, 2014). "Therefore, in patients with deactivating NF2 mutations, one could hypothesize that an mTOR inhibitor would restore merlin's inhibition of mTOR and arrest tumor formation." (PMID 24393766, 2014). "Considering that the effects of anti-angiogenesis treatments on endothelial cells are equivalent for any patient, the different responses to the drugs may be attributed to the genetic variability of tumor cells expressing the target receptors and/or over-activating the mTOR pathway." (PMID 24676409, 2014). "Interestingly, EGFRvIII expression and PTEN loss sensitized tumor cells to CC214 compounds, thereby implying that GBM cells with higher levels of PI3K signaling may be more sensitive to the interruption of mTOR signaling." (PMID 25610711, 2014). "Additionally, Amblyomin-X increased the expression of various chains of the molecular motor dynein in tumor cells, modulated specific ubiquitin linkage signaling and inhibited autophagy activation by modulating mTOR, LC3 and AMBRA1 with probable dynein involvement." (PMID 25479096, 2014). "Given that the TCGA tumor data demonstrated an inverse relationship between the loss of Rictor expression and miR-155HG expression in relation to ERα status and that Rictor expression was repressed in our MCF7-miR155 cell line, we next sought to determine the effects of miR-155 on mTOR signaling." (PMID 25283550, 2014). "However, there may be constraints to their evolution, exemplified by the activation of the mTOR pathway in all tumor regions." (PMID 25159823, 2014). "In addition, further investigation is needed to determine whether primary tumor site or other clinical and molecular factors can impact response to mTOR inhibition." (PMID 25092520, 2014). "In MM multicellular spheroids and MM tumor fragment spheroids, the role of mTOR in mediating survival signals has been assessed in two in vitro clinically relevant three-dimensional settings, suggesting that inhibition of mTOR may provide a valid nontoxic therapy for MM." (PMID 28548074, 2014). "Since MGMT is a suicide protein that is degraded upon binding to and repairing TMZ-induced O6-methylguanine adducts, it has been hypothesized that inhibition of translation via the mTOR signalling pathway could generate a tumour-specific reduction in MGMT protein and increase TMZ sensitivity." (PMID 24909675, 2014). "Therefore, inhibitors of mTOR are both tumor suppressors and gero-suppressors." (PMID 25587030, 2014).
tumor (continued). "Having confirmed that the loss of LKB1 in our model is responsible for enhanced metabolic activity, we were interested in whether treatment of LKB1−/−NIC mice in vivo with compounds that target the PI3K pathway and mTOR would be effective at inhibiting tumor growth." (PMID 25436981, 2014). "However, how to characterize tumor or patient factors so as to choose potential patients who will benefit from mTOR inhibitors may need more investigations." (PMID 24886512, 2014). "Thus, mTOR has become a popular target for new therapeutics to inhibit tumor cell growth." (PMID 25089218, 2014). "Targeting the mTOR signaling pathway could represent an effective tumor treatment strategy." (PMID 25153728, 2014). "Similarly, exposure to high levels of extracellular ATP can also tilt the signaling mechanism from a P2X7-phosphatidylinositol 3-kinase/Akt-mediated growth pathway to a novel P2X7-AMPK-mammalian target of rapamycin (mTOR)-mediated autophagic pathway, as observed in tumor cells." (PMID 25225473, 2014). "Therefore, the mTOR inhibitor may also be a potential candidate for the treatment of this type of tumor." (PMID 24348822, 2014). "Notably, the path included a subclonal deletion of the tumor suppressor TSC1 (tuberous sclerosis 1) that may activate the mammalian target of rapamycin (mTOR) pathway and promote tumor development." (PMID 25160065, 2014). "In the current studies, we also explored tumor growth and biochemical analysis of chemoresistant clones recovered from xenograft and examined whether combinational treatment of these cells with inhibitors of Aurora-A, mTOR and Akt could cooperate in tumor suppression." (PMID 23383195, 2013). "Indeed, reports documenting that AMPK significantly enhances 5-FU antitumor effects via COX-2 suppression and inhibits the mTOR signaling pathway that regulates tumor growth may support our observations." (PMID 23457527, 2013). "Therefore, we hypothesized that mTORC2 plays an important role in cell growth and proliferation and that targeting mTOR with specific mTOR inhibitors would produce better anti-tumor effects after TKI-acquired resistance." (PMID 23874880, 2013). "Moreover, as mTOR plays a central role in the autophagy pathway, TCMs that are able to induce tumor cell death through mTOR may potentially induce autophagy." (PMID 23760551, 2013). "There is even evidence that, under mTOR inhibition, an immune response to one foreign entity (for example, an organ transplant) may be simultaneously completely different to that of another (for example, tumour or microorganism)." (PMID 24565200, 2013). "Notably, treatments with pharmacologic inhibitors of EGFR or mTor are cytostatic at best in a subset of patients, indicating that other, unidentified factors or compensatory signals affect the survival and growth of tumor cells." (PMID 23459592, 2013). "Thus, although it appears to be an attractive hypothesis, the connection between deregulated Rheb/mTor signaling, suppression of autophagy, and the development of tumours requires further investigation in depth." (PMID 24216995, 2013). "Targeting mTOR in combination might be efficacious in patients with this tumor types." (PMID 23509459, 2013). "However, although there are limited data (n = 22), an association between BRCA1/2 loss and activation of the PIK3CA/mTOR pathway in human tumours has not been confirmed." (PMID 23971979, 2013). "Thus, activation of Ras signaling in OCCC may be the basis of the anti-tumor effect of mTOR inhibitors." (PMID 23502469, 2013).
tumor (continued). "Interestingly, our observations of time- and dose-dependent alterations of mTOR signaling by extracellular ATP suggest the possibility that mTOR also might function as a sensor for extracellular ATP levels in the tumor microenvironment." (PMID 23565201, 2013). "Unlike blood vessel angiogenesis, rapalogues effects on tumor-associated lymphangiogenesis are not well understood, but could provide critical additional target for mTOR inhibitors in the treatment of HNSCC." (PMID 23815869, 2013). "Therefore, we next tested whether ectopic VEGF expression in our isogenic cell lines could rescue tumor cells from the antitumor effects of the active site mTOR inhibitor, pp242." (PMID 23533410, 2013). "Of note, the occasional wide variation in the CIs might indicate that the association of different mTOR inhibitors and tumor types with FAEs might be different, but there was lack of statistical power to demonstrate a significant difference." (PMID 23785409, 2013). "Interestingly, LuCaP23.1 is a PTEN expressing tumor, but with intrinsic mTOR pathway activation." (PMID 24353195, 2013). "Taken together, these data suggest that the PI3K/PTEN/Akt/mTOR pathway may represent an important therapeutic target for HCC treatment in patients with differing etiologies that lead to the development of this aggressive tumor." (PMID 22470194, 2012). "However, pure mTOR inhibition (alone or in combination with other cytostatics) should be carefully reconsidered, because inhibition of mTOR results in activation of Akt in some tumor entities including RMS (this study)." (PMID 23300809, 2012). "Indeed, many negative regulators of mTOR signalling are known human tumour suppressors." (PMID 22479207, 2012). "Furthermore, siRNA-mediated knockdown of mTOR partially phenocopied miR-99a restoration suggesting that the tumor suppressive role of miR-99a may be mediated primarily through mTOR regulation." (PMID 23173671, 2012). "Therefore, there is an emergent need to identify predictive markers of response that may be useful to prospectively select patients bearing tumours which may respond and benefit from mTOR inhibition therapies." (PMID 22408430, 2012). "Furthermore, siRNA-mediated knockdown of mTOR partially phenocopied the effect of miR-99a overexpression, suggesting that the tumor suppressive role of miR-99a may be mediated primarily through mTOR regulation." (PMID 23173671, 2012). "The recent identification of mTOR as a downstream target of Fbxw7 suggests that germline or somatic changes may affect tumor responses to known inhibitors of the mTOR pathway such as rapamycin, and such investigations are presently in progress in this laboratory." (PMID 22348067, 2012). "Thus, inhibitors of mTOR have emerged as a tool to control tumor growth." (PMID 22758623, 2011). "Taken together, these data suggest that Ras/PI3K/Akt/mTOR pathway may represent an important therapeutic target for the treatment of HCC among patients with differing etiologies that lead to the development of this aggressive tumor." (PMID 21422497, 2011). "In addition, mTOR inhibitors sensitize tumor cells to DNA-damaging agents in vitro." (PMID 22091432, 2011). "Thus, mTOR inhibition by rapamycin could block tumor growth from the first implantation but enhance continuous growth of the secondary tumors derived from H-Ras-transformed mouse liver cells." (PMID 22145042, 2011). "Therefore combining mTOR and Mek inhibitors might have synergistic effects both on tumor cells and on the tumor vasculature." (PMID 24212820, 2011). "In addition, an emerging role of mTOR in the tumor microenvironment has been suggested." (PMID 24212820, 2011). "Thus, the anti-tumour effects noted by inhibiting mTOR may be related to antiproliferative effects within tumour cells as well endothelial cells." (PMID 19128503, 2009).